SMARCA4 (SWI/SNF related BAF chromatin remodeling complex subunit ATPase 4)
Diseases named in the same sentence as SMARCA4 in open-access papers (continued):
Sharing a sentence is not in itself a finding about the gene and the disease.
cancer (continued). "SMARCA4 expression was higher in SCLC lines than in any other solid tumor represented in the Cancer Cell Line Encyclopedia (CCLE)." (PMID 39080761, 2024). "A pan-cancer analysis based on the data from TCGA and GTEx database revealed that SMARCA4 was observed upregulated in most cancers, which was correlated with poor overall survival in ACC, MESO, SARC, and SKCM48." (PMID 38225273, 2024). "This suggests the need to investigate further the role of this pathway in autophagy in the context of SMARCA4 and autophagy SMARCA4 in different cancer types." (PMID 39697230, 2024). "Herein, we present four rare cases of gastric SMARCA4-UTs and provide insight into the clinicopathological characteristics and genetic alterations of these highly aggressive malignant tumors." (PMID 38877473, 2024). "Our study has revealed a potent vulnerability of SMARCA4-mutant cancer cells to dual inhibition of ROCK1/2 and OXPHOS." (PMID 39345502, 2024). "The potential use of allosteric inhibitors of SMARCA4/SMARCA2 is a significant breakthrough for a cancer type that has few treatment options." (PMID 38390898, 2024). "We first sought to evaluate relative expression levels of SMARCA4 across the spectrum of human cancers." (PMID 39080761, 2024). "Targeted EZH2 inhibitors are currently under investigation for the treatment of cancers with SWI/SNF complex protein abnormalities such as SMARCA4-UT." (PMID 38903719, 2024). "By using the depmap online platform (depmap.org), we observed that NB exhibited significantly higher SMARCA4 mRNA levels compared to most other cancer types." (PMID 39174852, 2024). "The frontal sinus was affected in one case, accounting for 20% of the carcinomas with altered SMARCA4 expression." (PMID 39590317, 2024). "In this group of carcinomas, the partial inactivation of SMARCA4 was more prevalent in women (60%) than in men (40%)." (PMID 39590317, 2024). "Two new studies exploring PROTAC-mediated degradation of SMARCA2 for cancer therapy solve an apparently intractable selectivity challenge with SMARCA4 by utilising the requirement for a productive ternary complex between the protein, PROTAC and ligase complex." (PMID 36720862, 2023). "In our investigation, two patients with a stage IA disease and a germline PV in SMARCA4 remained cancer‐free for 7 years (patient #1) and 5 years (patient #2), respectively, following platinum‐based multi‐agent regimen." (PMID 37345881, 2023). "Identification of cases of malignant tumors with a SMARCA4 deletion in the uterus is important; investigation of the role of the immune microenvironment from various perspectives in SDUS is needed." (PMID 37194064, 2023). "Strikingly, R-loop mutation burden was significantly higher in tumors holding SMARCA4, SMARCA5 and INO80 gene deficiencies, consistent with a direct role of these activities preventing R-loop mutagenesis in cancer." (PMID 37898641, 2023). "SMARCA4 the ATPase is a common subunit with all three BAF complexes, and it is also frequently mutated in various cancers including breast, lung, and colorectal cancers." (PMID 37093326, 2023). "Recently, we have demonstrated that SMARCA4 exhibit a consistent positive correlation with cancer stemness (assessed based on transcriptomic features of TCGA cancers)." (PMID 36674511, 2023). "Shared recurrent mutations in both NDD and cancer included those localized to the C-terminal domain of SMARCB1, the SMARCA4 N terminus, as well as within PBRM1 and ACTB subunits." (PMID 37500730, 2023).
cancer (continued). "Therefore, the long-term effects of alanine supplementation require further investigation for patients with SMARCA4/2-deficient cancers along with the development of SLC38A2 inhibitors, that may also prove efficacious for other SLC38A2-dependent tumors such as pancreatic cancer." (PMID 37210563, 2023). "SMARCA4-deleted cancer cells are highly dependent on the paralog SMARCA2 for their survival, and ARID1B is required for the survival of ARID1A-depleted cells as well." (PMID 37371564, 2023). "A comprehensive analysis of SMARCA4 revealed that it is significantly expressed in numerous types of cancer and is related with poor overall survival in some tumors." (PMID 37217462, 2023). "Elevated SMARCA4 expression has also been reported in many cancers including colorectal, gastric, prostate, and intestinal cancers." (PMID 37093326, 2023). "The role of SMARCA4 in cancer progression remains controversial, which makes the function of its mutation more complicated." (PMID 36922568, 2023). "In contrast, alanine, readily available at low cost, can be easily added as a dietary supplement to enhance current standard treatments for SMARCA4/2-deficent cancers." (PMID 37210563, 2023). "Different from the A1186T mutation, cancer cells carrying homozygous G1232D or G1232S mutations depend on SMARCA2 for survival, supporting the complete functional inactivation of SMARCA4." (PMID 36633435, 2023). "Together, these results establish that SMARCA4/2 loss directly reduces the transcription of SLC2A1, resulting in GLUT1 deficiency and subsequent impaired glucose uptake in these cancer cells." (PMID 37210563, 2023). "Due to the mutual exclusivity of SMARCA4 and SMARCA2 as catalytic subunits of the SWI/SNF complex, a common approach to targeted treatment of SMARCA4-mutant cancers is synthetic lethality." (PMID 37433987, 2023). "EZH2 inhibition led to impaired proliferation of several human cancer cell lines with mutant SWI/SNF genes including BRG1 (SMARCA4), PBRM, and ARID1A." (PMID 38275587, 2023). "Furthermore, we present unexpected predictive models of several DDR deficiencies; ATRX and IDH1 deficiency in cancers of the central nervous systems (CNSs), HERC2 and CDKN2A deficiency in skin, PTEN deficiency in cancers of the CNS and uterus, and SMARCA4 deficiency in cancers of unknown primary." (PMID 36883553, 2023). "Whereas ARID1A and SMARCA4 have more dominant roles in cancer, their closely paralogs, ARID1B and SMARCA2, frequently mutated in CSS and NCBRS, respectively." (PMID 36633435, 2023). "SWI/SNF complex-deficient carcinomas, defined by loss of one of the SWI/SNF complex genes, include two major subtypes: SMARCB1- and SMARCA4-deficient sinonasal carcinoma." (PMID 36937407, 2023). "A recent study by Farnaby developed an optimized chemical ACBI1 that cooperatively targets SMARCA2, SMARCA4, and PBRM1, exhibiting significant antiproliferative and cell death-inducing effects in SMARCA4-mutant cancer cells." (PMID 36361605, 2022). "Due to the concept that SMARCA4-mutant cancers are vulnerable to SMARCA2 inhibition, selectively degrading SMARCA2 has been an important therapeutic strategy." (PMID 36361605, 2022). "We have recently reported that the significant upregulation of the BrD family members ATAD2 and SMARCA4 and downregulation of SMARCA2 are associated with enriched cancer stemness." (PMID 36614001, 2022). "The postHSA-containing Hub of SMARCA4 and HSA-containing ARP module are essential for the function of SWI/SNF complexes and cancer-associated gain-of-function mutations are enriched on the Hub28–31." (PMID 36496390, 2022). "It is also conceivable that SMARCA4 levels change reversibly, depending on signals from the cancer microenvironment." (PMID 35323214, 2022).
cancer (continued). "The CNV analysis by sequencing (CNV-seq) revealed five cancer-associated genes as the most frequent with gains (NOTCH1, MYC, NUMA1, PLAG1, and RAD21), while 30% of the tumors showed SMARCA4 with loss." (PMID 35884575, 2022). "Our results demonstrate that significant upregulation of ATAD2 and SMARCA4, and downregulation of SMARCA2 is consistently associated with enriched cancer stem cell‐like phenotype, respectively." (PMID 35049055, 2022). "Eventually, seven ATPCR encoding genes, including ATRX, CHD5, CHD7, SMARCA4, SMARCA2, EP400, and ACTB, were identified as driver genes by at least two algorithms in certain cancer types." (PMID 35789070, 2022). "The BRG1 (SMARCA4) subunit of the SWI/SNF chromatin remodelling complex is frequently lost in cancer." (PMID 35365638, 2022). "Among the six SWI/SNF genes, ARID1A and SMARCB1 were, respectively, the most and least frequently mutated genes in the majority of the cancer types (ARID1A, 10.7%; SMARCA4, 6.0%; ARID1B, 4.7%; ARID2, 4.0%; PBRM1, 3.5%; SMARCB1, 1.3%)." (PMID 36371186, 2022). "SMARCA2 and SMARCA4 exhibit a synthetic lethal relationship in cancer that can be exploited therapeutically." (PMID 35323214, 2022). "About 2/3 of undifferentiated/dedifferentiated carcinoma show the loss of one of three crucial proteins of the SWI/SNF complex, i.e., ARID1B, SMARCA4/BRG1, and SMARCB1/INI1." (PMID 36232987, 2022). "Our data show that SMARCA4/2-deficient cancer cells are resistant to cisplatin in part through suppression of IP3R3 and that ectopic IP3R3 expression can sensitize these cancer cells to cisplatin-induced apoptosis." (PMID 34518526, 2021). "The present work illustrated a comprehensive workflow for pan-cancer analysis and thoroughly investigated the role of the SMARCA4 in cancers." (PMID 34675941, 2021). "Our findings suggest that SMARCA4 influences the prognosis of cancer patients, while the role of SMARCA4 in different cancer types varies." (PMID 34675941, 2021). "Here, we show that cancer cells that lack SMARCA4 have a defective regulation of H3K27ac/H3K27me3 and exhibit low levels of KDM6s, indicative of a deficient activity of these demethylases." (PMID 34262032, 2021). "In some cases, synthetic lethality is caused by the concomitant knockout of two mutually exclusive paralogues: Tumours with a SMARCA4 deficiency are sensitive to SMARCA2 depletion, and ARID1B is required for survival of ARID1A-mutant cancers." (PMID 33941852, 2021). "SWI/SNF subunits are the most commonly mutated chromatin-regulatory complexes in human cancer, mutated in 19.6% cancers, with subunits ARID1A, PBRM1, SMARCA4, and ARID2 already part of routine cancer diagnostics." (PMID 34944438, 2021). "The mean expression of SMARCA4 was significantly increased in both the cancer cell lines and the transformed cell lines compared to the normal cells (p = 0.0148 and p = 0.0353, respectively)." (PMID 33596994, 2021). "The discovery that the SMARCA4 plays an essential role in cancer immunology highlights the importance of future studies of larger cohorts of patients to further determine the clinical feasibility of immune checkpoint inhibitors." (PMID 34675941, 2021). "ImmuneScore and StromalScore were integrated to evaluate the relationship between SMARCA4 expression and immune infiltration across cancers." (PMID 34675941, 2021). "For both cancer types, cell lines with low SMARCA4 expression (bottom quartile) also expressed lower levels of ITPR3 compared to the rest of cell lines with high SMARCA4 expression." (PMID 34518526, 2021). "Our study examined the roles of SMARCA4/2 in regulating chemotherapy response and apoptosis induction using cancer cell lines that naturally harbor SMARAC4/2 alterations." (PMID 34518526, 2021). "SMARCA4 has been shown to be involved in developmental processes, transcriptional regulation, DNA repair, cell cycle control, and cancer." (PMID 34675941, 2021).
cancer (continued). "In summary, the present study reveals that SMARCA4 is correlated with the prognosis of patients with cancer and immune infiltration across diverse cancers." (PMID 34675941, 2021). "Although its role in cancer progression remains a constant topic of debate, interest in elucidating the roles of SMARCA4 in cancer progression is at an all-time high." (PMID 33853662, 2021). "This is different from previous studies employing RNAi-mediated SMARCA4 knockdown in SMARCA4-proficient cancer cells which led to enhanced response to DNA damaging agents." (PMID 34518526, 2021). "In our analysis, SMARCA4 expression is related with the expression of MMR genes in multiple cancer types." (PMID 34675941, 2021). "It is reasonable to extrapolate our finding to a larger scenario wherein SMARCA4, through coordinating the actions of multiple transcription factors or epigenetic regulators, modulates a transcriptional program that promotes cancer progression." (PMID 33853662, 2021). "The top 100 genes that correlate with SMARCA4 expression were obtained via GEPIA2 tool to combine pan-cancer expression of TCGA." (PMID 34675941, 2021). "More efforts are needed to explore the role of SMARCA4 in cancer and the value of SMARCA4 as a potential target of anticancer therapy." (PMID 34675941, 2021). "PITPNC1 has been shown to be overexpressed in metastatic breast, colon, and melanoma cancers, and SMARCA4 is a marker of poor prognosis in many types of cancer." (PMID 34439480, 2021). "SMARCA4 has been reported to be a dominant gene involved in cancer cell proliferation, migration, invasion, etc. in some cancers, such as colorectal cancer and leukemia." (PMID 34083693, 2021). "The results show that overexpression of SMARCA4 is correlated with a worse prognosis in some cancer types." (PMID 34675941, 2021). "SMARCA4 is the core catalytic subunit of the mammalian SWI/SNF complex and is known to be mutated in many cancers." (PMID 33144586, 2020). "SMARCA4 (also known as BRG1) has been shown to be involved in various developmental processes, transcriptional regulation, DNA repair, cell cycle regulation, and cancer." (PMID 32708644, 2020). "Here we explore SMARCA4 alterations in 131,668 cancer patients and functionally profile their remodeling activity and ability to compensate for SMARCA2 loss." (PMID 33144586, 2020). "Using large patient datasets, patient-derived organoids and cancer cell lines, we identify mSWI/SNF subunits that are deregulated in NEPC and demonstrate that SMARCA4 (BRG1) overexpression is associated with aggressive disease." (PMID 33144576, 2020). "Here we report the genomic profiling of solid tumors from 131,668 cancer patients, identifying 9434 patients with one or more SMARCA4 gene alterations." (PMID 33144586, 2020). "Our data suggest that SMARCA4 inhibition would allow for a selective, cancer-cell directed therapy sparing normal, SMARCA2-expressing cells and tissues." (PMID 31406271, 2019). "Similar to the ARID1A/ARID1B functional dependency, SMARCA4 mutant cancer cells showed sensitivity to SMARCA2 depletion." (PMID 31769422, 2019). "We set out to uncover vulnerabilities in SMARCA4-deficient SCCOHT using synthetic lethal screens, which are powerful tools to identify drug targets and help derive cancer-specific therapies that have minimal side effects in normal tissue." (PMID 30718512, 2019). "Mutations in SWI/SNF and chromatin-remodeling complex (SMARCA4, COL6A3, RYR2, and SPEG) contributed to cancer and neurological disorders." (PMID 31428092, 2019). "ACBI1 inhibited cell proliferation and induced apoptosis in leukemia cell lines with an intact BAF complex and SMARCA4-mutant cancer cells." (PMID 31769422, 2019). "In the present study, we performed integrated copy number analysis and expression profiling at this locus and a putative cancer gene, SMARCA4/BRG1, was uncovered in this region." (PMID 29352111, 2018).
cancer (continued). "This comparison confirmed significant positive enrichment in cancer for all but 2 AR target gene sets (SMARCA4- and NCOA2-dependent)." (PMID 28826481, 2017). "Mutations in other cancer genes including CBFB, IDH1, JAK1, KMT2A, SMAD4, and SMARCA4 were found in one MBC each." (PMID 29214215, 2017). "SMARCA4 (or BRG1) is a catalytic subunit of the SWI/SNF chromatin remodeling complex, which undergoes somatic mutation in multiple cancers." (PMID 28594900, 2017). "The post-treatment cancer retained its pathogenic CDKN2A and SMARCA4 mutations and gained a low VAF, truncating ARID1A change." (PMID 27045317, 2016). "Other frequently mutated EAC driver genes included NOTCH1 (N=8 cancers), ARID1A (N=7), CNTNAP5 (N=3), PIK3CA (N=3) and SMARCA4 (N=3)." (PMID 27045317, 2016). "Due to high aggressiveness of the SCCHT, it seems reasonable to offer the patients with this cancer and their families a molecular diagnostics of the SMARCA4 gene." (PMID 25886974, 2015). "Nevertheless, because of high aggressiveness of the SCCHT, a molecular diagnostics of the SMARCA4 gene and careful follow-up should be offered to patients with this cancer and their families." (PMID 25886974, 2015). "Aside from mutation‐specific vulnerabilities within BAF complexes themselves, cancers with mutations in the most frequently affected BAF subunits ARID1A, SMARCA4/2, and SMARCB1255 have several other synthetic lethal interactions that can be leveraged therapeutically." (PMID 40181550, 2026). "Therefore, the selective depletion of SMARCA2 is particularly toxic for the respective cancer cells, while non‐malignant normal cells can compensate for SMARCA2 loss via SMARCA4 function." (PMID 40181550, 2026). "Here, using a SMARCA4-deficient LUAD cellular model, we show that SMARCA4 overexpression reorganizes enhancer landscapes and establishes a cooperative transcriptional network involving FOSL1, thereby promoting cancer cell proliferation and tumorigenic phenotypes." (PMID 42010258, 2026). "Due to the rarity of germline pathogenic SMARCA4 variants, standardized recommendations for intensified cancer surveillance and preventive strategies are lacking." (PMID 41528496, 2026). "Furthermore, treatment with CBP/p300 dual inhibitor suppressed the growth of xenografts derived from SMARCA4/SMARCA2-deficient and SS18–SSX fusion cancer cells, resulting from repression of KREMEN2 and induction of apoptosis." (PMID 39625239, 2025). "The loss of BRG1 in various human cancers, including nearly all SMARCA4-DTS and SCCOHT cancers and at least 10% of NSCLC cancers, which often have a typical, poorly differentiated rhabdoid morphology and highly aggressive clinical features, supports this premise." (PMID 41008934, 2025). "Another SWI/SNF core subunit SMARCA4 also participates the cancer cell plasticity." (PMID 41415713, 2025). "Thus, SMARCA4/SMARCA2-deficient and SS18–SSX fusion cancer cells depend on the expression of KREMEN2." (PMID 39625239, 2025). "To further confirm that KREMEN2 is a determinant of synthetic lethality through simultaneous inhibition of CBP/p300 in SMARCA4/SMARCA2-deficient cells and SS18–SSX fusion cancer cells, we investigated whether depleting KREMEN2 affects cell viability." (PMID 39625239, 2025). "Except for case 3, in which heterozygous mutation of SMARCA4 were detected in the blood samples of father and child, no hereditary cancer predisposition were detected in the other five cases." (PMID 41148473, 2025). "This study further suggested that SMARCA4 might play an important role in hypoxia-induced transcription of genes involved in cancer cell proliferation and migration." (PMID 39888726, 2025). "Designing prospective clinical SMARCA4-mutated or SMARCA4/KRAS co-mutated NSCLC trials to evaluate targeted therapies and immunotherapy may lead to a better understanding of how to improve cancer patients’ outcomes and survival rates." (PMID 39063938, 2024).